CDKN2A (cyclin dependent kinase inhibitor 2A)
Diseases named in the same sentence as CDKN2A in open-access papers (continued):
Sharing a sentence is not in itself a finding about the gene and the disease.
endometrial cancer (39 papers, 2014 to 2026). Primary or metastatic malignant neoplasm involving the endometrium (mucous membrane that lines the endometrial cavity). "In summary, by collecting and analyzing the transcript information of endometrial cancer samples from TCGA database, we identified four prognosis-associated autophagy genes (CDKN2A, PTK6, ERBB2, and BIRC5)." (PMID 33109128, 2020). "In the present study, we identified elevated CDKN2A expression as an independent risk factor for endometrial cancer, with higher levels of CDKN2A expression corresponding with worse prognosis for patients with endometrial cancer." (PMID 33109128, 2020). "We constructed a prognostic model of endometrial cancer containing four risk ARGs (CDKN2A, PTK6, ERBB2, and BIRC5) using multivariate and univariate Cox, and LASSO regression analyses." (PMID 33109128, 2020). "Inactivation of CDKN2A, through loss of heterozygosity or hypermethylation of its promoter, has been reported in endometriosis and endometrial cancer." (PMID 24676469, 2014). "CDKN2A is considered to play a key clinical role in assessing various prognostic mechanisms of endometrial cancer, possibly related to cell cycle dysregulation caused by CDKN2A deletion." (PMID 39931061, 2025). "The HPA database provided IHC images of endometrial cancer and normal endometrial tissues, allowing us to confirm the differential expression of CDKN2A, SELENOP, GSN, PGR, and TRPC1 at the protein level." (PMID 41244925, 2025). "The expression of CDKN2A and GLS is also positively associated with the abundance of certain immune cells in endometrial cancer." (PMID 36588699, 2022). "In this study, L1CAM, PRKCI and CDKN2A were the most relevant genes affecting survival in endometrial cancer, with high amounts reflecting poor prognosis." (PMID 34659539, 2021). "In another study, a six-gene prognostic signature, including CTSW, PCSK4, LRRC8D, TNFRSF18, IHH, and CDKN2A, in endometrial cancer was also established using robust likelihood-based survival modeling." (PMID 31781484, 2019). "Regarding field cancerization, methylation of hMLH1, CDKN2A/P16 and SFRP1 has been recently indicated to be associated with malignant transition in endometrial cancer." (PMID 25405986, 2014). "Similar results have been reported in other types of cancer, for example, CDKN2A is upregulated in endometrial cancer and may contribute to its pathogenesis." (PMID 36843949, 2023). "Another study also suggested CDKN2A as a prognostic biomarker in human endometrial cancer." (PMID 35937995, 2022). "A possible explanation for this is that CDKN2A overexpression in the stroma might affect the tumor microenvironment through the secretion of cytokines and proteases and promote the growth of endometrial cancer." (PMID 33109128, 2020). "Immunohistochemistry revealed ISH scores for four risk ARGs (CDKN2A, ERBB2, PTK6, and BRIC5) were significantly higher in endometrial cancer tissue than in healthy endometrial tissue, which suggested that these genes are highly expressed in endometrial cancer tissues." (PMID 33109128, 2020). "Importantly, expression levels of the tumour suppressor genes CDKN2A and PIK3CA, which are deleted or mutated in endometrial cancer, were decreased in CTCF-altered samples (p = 0.0006 and p = 0.0007, respectively)." (PMID 30513694, 2018). "We evaluated whether rs17761446 worked as a cis-regulatory element of ANRIL, CDKN2A, and CDKN2B with the allele specific expression (ASE) analysis using eutopic endometrial tissues and endometrial carcinoma cell lines." (PMID 27055116, 2016). "The higher expression of FOXA1 in metastases compared to their primary tumor counterparts, and the association between protein expression of FOXA1 and CDKN2A mRNA only in metastatic lesions, may indicate a change in the role of FOXA1 during endometrial cancer progression." (PMID 24849812, 2014).
endometrial cancer (continued). "IHC images revealed that CDKN2A, SELENOP, and TRPC1 were expressed at higher levels in endometrial carcinoma tissues compared to normal endometrial tissues, consistent with their mRNA upregulation in high-risk patients." (PMID 41244925, 2025). "Some of these genes, such as CDKN2A, E2F1, and ERBB2, have been characterized in endometrial cancer tumorigenesis." (PMID 35205261, 2022). "Five most significant genes were selected, including L1CAM (L1 cell adhesion molecule), PRKCI, ESR1, CDKN2A and VIM, to construct a prognostic model for endometrial cancer." (PMID 34659539, 2021). "Our prognostic model assessing four ARGs (CDKN2A, PTK6, ERBB2, and BIRC5) suggested their potential as independent predictive biomarkers and therapeutic targets for endometrial cancer." (PMID 33109128, 2020). "Immunohistochemistry suggested that among the four ARGs the protein levels of CDKN2A, PTK6, ERBB2, and BIRC5 were higher in endometrial cancer than healthy endometrial tissue." (PMID 33109128, 2020). "Four ARGs (CDKN2A, PTK6, ERBB2 and BIRC5) were selected to establish a prognostic model of endometrial cancer." (PMID 33109128, 2020). "The first gene regulates some onco-suppressors such as CDKN2B, CDKN2A and ARF; its inactivation has been correlated with the development of endometriosic foci and endometrial carcinoma." (PMID 32143537, 2020). "Previous studies demonstrated that the loss of function of the CDKN2A/p16/INK4A gene is mainly caused by the hypermethylation of CDKN2A, however, whether or not it is associated with the incidence and clinicopathological characteristics of endometrial carcinoma (EC) remains unclear." (PMID 26283007, 2015). "Protein data for many genes such as CDKN2A were absent from the original TCGA datasets; even so, our study corroborates the reported enrichment of CDKN2A transcript levels in Black patients with endometrial cancer." (PMID 37345032, 2023).
metastatic tumors (38 papers, 2003 to 2026). "Of 24,503 patients with complete OS data, CDKN2A-DEL patients had the most FGA, MSI score and largest number of patients having metastatic disease, while those CDKN2A-DELMUT patients had the biggest TMB and mutation count." (PMID 38822443, 2024). "In the group of clinically localised ccRCC, the LOH in the CDKN2A region was associated with a higher risk of recurrence or development of metastatic disease, as determined by univariate analysis (p = 0.023; HR 4.04)." (PMID 27682877, 2016). "The Cdkn2a/b deletions were highly concordant between primary and metastatic tumors and they mirrored the genetic association of SMAD4 alterations with homozygous CDKN2A/B deletions in the MSK-IMPACT cohort of human PDAC." (PMID 40999053, 2025). "Conversely, CDKN2A-MUT patients exhibited longer OS than CDKN2A-WT patients with metastatic disease (HR, 0.59; 95% CI, 0.40–0.87)." (PMID 38822443, 2024). "Samples of metastatic tumors exhibited a higher proportion of elevated PD-L1 expression, a greater number of pathway alterations, and a higher occurrence of CDKN2A copy number deletions than primary samples." (PMID 39323996, 2024). "Patients with CDKN2A ALT tended to have metastatic disease, be male and stage IV." (PMID 38822443, 2024). "Previous research in a similarly sized cohort of patients with paired primary and matched metastatic tumour samples, identified somatic copy number losses at 9p21 (CDKN2A) and 14q (L2HGDH, HIF1A) as critical molecular alterations towards the development of metastatic disease in patients with ccRCC." (PMID 35231161, 2022). "It is also reported that CDKN2A is lost in locally advanced or metastatic tumor tissues." (PMID 35311137, 2022). "CDKN2A copy number loss in metastatic disease was not significantly different form primary tumours (p = 0.225, q = 0.342)." (PMID 31916407, 2020). "Of the 4 patients who developed disseminated disease, 2 did not have biallellic CDKN2A loss in their primary or metastatic tumor and 2 had biallelic deletion in a subset of melanocytes that were not present at distant metastatic sites." (PMID 26061100, 2015). "CDKN2A and CKDN2B deletions and BRAF and TERT amplifications were common in the metastatic tumors of SUM and AM." (PMID 37686691, 2023). "Our research showed that CDKN2A-MUT patients had shorter survival times than CDKN2A-WT patients in the MSK MetTropism and TCGA cohorts, but longer OS in the MSK-IMPACT cohort with ICIs treatment, particularly in patients having metastatic disease." (PMID 38822443, 2024). "Furthermore, CDKN2A deletion, PTEN deletion, and MYC amplification occurred more frequently in metastatic (7.4%, 3.3%, and 6.7%, respectively) than non-metastatic disease (4.2%, 1.6%, and 3.8%, respectively)." (PMID 36187555, 2022). "However, it was noteworthy that CDKN2A ALT was favored in the prognosis of patients treated by ICIs from cancer patients having metastatic disease and not primary cancers patients in the MSK-IMPACT cohort." (PMID 38822443, 2024). "In Patient 3, three genomic loci—9p21 (CDKN2A and MTAP), 11q13 (OVOL1), and 11p15 (HRAS)—were homozygously deleted in the primary site tumor population (3PST) but not in the metastatic tumor population (3MT)." (PMID 40004220, 2025).
metastatic tumors (continued). "Patients with CDKN2A ALT who were not treated with ICIs had a shorter OS, while those with CDKN2A ALT who were treated with ICIs, especially those with metastatic disease, had a longer OS." (PMID 38822443, 2024).
oropharyngeal carcinoma (37 papers, 2008 to 2026). Carcinoma, predominantly squamous cell, arising from the epithelial cells of the oropharynx. "Overall, this study provides evidence of epigenetic changes to the downstream region of the CDKN2A locus in HPV+ oropharyngeal cancer that are associated with changes in expression of the coded protein products." (PMID 25619363, 2015). "Tumor suppressor protein p16 INK4a is encoded by the CDKN2A gene and is considered a prognostic factor for positive-HPV oropharyngeal cancer." (PMID 36358782, 2022). "CDKN2A has been classified as a tumor suppressor, methylation studies have detected promoter hypermethylation of CDKN2A in oral and oropharyngeal cancer tissue as well in OPL; therefore CDKN2A inactivation is in part due to promoter methylation." (PMID 35154165, 2022). "In order to further explain differences between p16 expression and HPV-DNA in oropharyngeal cancer we performed Methylation-Specific PCR (MSP) to evaluate CDKN2a/INK4a promoter inactivation." (PMID 22376902, 2012). "However, CDKN2A expression is considered even more imperative in HPV-driven HNC, as p16INK4a expression itself is considered as an independent prognosticator of HPV-driven oropharyngeal cancer (OPC)." (PMID 32486347, 2020). "Finally, MSP showed that the methylation of CDKN2a/INK4a is a frequent epigenetic alteration in oropharyngeal cancer and revealed that p16 was inactivated in 75% of OPSCCs associated to alcohol and tobacco risk factors." (PMID 22376902, 2012). "Our data for HPV- oropharyngeal cancer indicate that the frequency of CCND1 amplification (in approximately 55% of cases) and CDKN2A/B deletions (in approximately 55% of cases) are higher than previously reported." (PMID 23718828, 2013).
brain tumors (36 papers, 2009 to 2026). "Analysis of 54 clinically diagnosed primary patient samples published on the PedcBioPortal from the Pediatric Brain Tumor Atlas (PBTA) shows that CDKN2A rarely has structural variants in ATRT, with only 2% of samples having a deep deletion." (PMID 41408661, 2025). "The co-existence of mutant BRAFV600E with CDKN2A loss suggests transformation into histologically higher-grade brain tumor, with more aggressive behavior and worse clinical course." (PMID 37138345, 2023). "Co‐occurrence of BRAFV600E and CDKN2A loss defines a subset of pediatric brain tumors that are responsive to combined treatment with BRAF and CDK4/6 inhibitors." (PMID 33769711, 2021). "MLPA analysis did not reveal any differences between DK-MG lines, other than EGFRvIII, with both lines having normal number of wild-type EGFR copies, hemizygous PTEN and NFkBIA, and CDKN2A deleted; all mutations reminiscent of brain tumors." (PMID 27004406, 2016). "Our findings demonstrate that Infinium EPIC Bead Chip analysis, which is routinely applied in molecular brain tumor classification, 34 is a reliable technique for detection of CDKN2A/B chromosomal losses." (PMID 41438586, 2026). "Several studies have investigated p16 protein detection as a surrogate biomarker for homozygous CDKN2A deletions in brain tumors." (PMID 40227557, 2025). "MCs and CDKN2A/B statuses were ascertained using the Heidelberg methylation brain tumor classifier v12.5 (v12.8 for selected cases)." (PMID 37998600, 2023). "1p, CDKN2A loss), and clinical (latency, location, dosimetry) aspects of RIG that can prove useful to distinguish RIG from de novo pHGG and recurrent pediatric brain tumors." (PMID 34545084, 2021). "CDKN2A loss has been previously reported in ST ependymoma and is known to be an indicator of adverse prognosis in RELA-fused ependymomas and other brain tumors such as IDH-mutated anaplastic astrocytoma." (PMID 32474813, 2020). "In order to study the prevalence of CDKN2A in brain tumors, we performed an in silico analysis of 1018 glioma tumors." (PMID 32516884, 2020). "We show that the combination therapy of adagrasib and abemaciclib led to good brain penetration and on-target activity in brain tumors carrying KRAS-G12C and CDKN2A loss and was able to provide survival benefit in an NSCLC brain metastasis model that did not respond to monotherapy." (PMID 40317086, 2025). "By contrast, no brain tumor formation was observed in the lentivirus injection with YAP1-MAMLD1 (without additional Cdkn2a loss), whereas small tumor or neoplastic lesions were detected upon additional co-injection of sgCdkn2a." (PMID 33228790, 2020). "Interestingly, a mouse model with a combination of CDKN2A−/− and a PDGFRA point mutation showed brain tumors with double minute chromosomes or ecDNA40, while another CDKN2A−/− mouse model that generated brain tumors after irradiation similarly had ecDNA41." (PMID 31992716, 2020). "Associations have been suggested for LFS-associated brain tumors with nonsense PVs in CASP9 (caspase-9), for a POT1 (protection of telomeres 1) missense variant with cardiac and breast angiosarcomas, and for CDKN2A PVs with hereditary sarcoma cases." (PMID 30086788, 2018). "Similar to cdkn2a/b inactivation of F0 tp53e7/e7 mutants, TALEN-mediated somatic inactivation of rb1 led to early onset of brain tumors in adult zebrafish." (PMID 28903419, 2017).
coronary artery disease (34 papers, 2007 to 2024). "Another recently published study examining the relationship between poor glycemic control and polymorphism in the 9p21 locus (close to the CDKN2A-2B genes) highlighted an increased risk of developing coronary artery disease in carriers of two risk alleles." (PMID 37513978, 2023). "This locus harbors multiple coronary artery disease (CAD) risk variants, including two functional variants reported to abrogate the function of an enhancer (ECAD9) by disrupting TEAD3 and STAT1 binding, thereby misregulating the expression of the target genes, CDKN2A/B (22, –24)." (PMID 37922325, 2023).